LINC01648 (long independently transcribed non-coding RNA 1648)
Gene: Long non-coding RNA gene on chromosome 1 (30,013,952 to 30,037,612, reverse strand). Ensembl gene ENSG00000233399.
Diseases named in the same sentence as LINC01648 in open-access papers:
LINC01648 is named in the same sentence as 1 disease in open-access papers, as found by Europe PMC text mining. Sharing a sentence is not in itself a finding about the gene and the disease. The quoted sentences say what the papers report.
prediabetes (1 paper, 2022). "We found two susceptibility loci in MRPS6/SLC5A3 genes associated with 2hPG, six loci in LINC01648, MATN1, CRAT37, and SLCO3A1 genes associated with HbA1C, and five loci in TRPM3/TMEM2 and MLYCD/OSGIN1 correlated to BMI in Hainan prediabetes." (PMID 35299963, 2022).